FGFR3 (fibroblast growth factor receptor 3)
Diseases named in the same sentence as FGFR3 in open-access papers (continued):
Sharing a sentence is not in itself a finding about the gene and the disease.
breast carcinoma (continued). "In contrast, miR-593-3p overexpression inhibits the malignant phenotype of breast cancer by targeting FGFR3." (PMID 38642144, 2024). "FGFR3 is a known target of microRNA-593-3p, and the overexpression of miR-593-3p down-regulates FGFR3 expression, which slows breast cancer progression." (PMID 39057065, 2024). "Although FGFR3 gene expression and FGFR3 are rarely found in breast cancer patients, these data suggest a potential oncogenic role for FGFR3." (PMID 35193394, 2022). "The FGFR1 and FGFR3 inhibitor BGJ398 was investigated in a phase II clinical trial for FGFR1-amplified lung cancer and FGFR1/2-amplified and FGFR3-mutant breast cancer." (PMID 34639155, 2021). "For an example, multiple kinase FGFR/vascular endothelial growth factor receptor (VEGR) inhibitor gained the promising results in breast cancer with FGFR/FGFR3 amplification." (PMID 33928031, 2021). "The TCGA and Metabric breast cancer datasets were interrogated to identify FGFR3 alterations and how they relate to breast cancer subtype and overall patient survival." (PMID 31987043, 2020). "While the roles of FGFR1 and FGFR2 in breast cancer have been studied in considerable detail, FGFR3 remains poorly characterized in this setting." (PMID 31987043, 2020). "Tomlinson and co-workers have also shown that the expression of FGFR3 is higher in a subset of tamoxifen-resistant ER+ breast cancers with respect to tamoxifen-sensitive ER+ breast tumors." (PMID 33081025, 2020). "Regarding the FGFR3 locus (4p16), its amplification has been detected in less than 1% of patients with breast cancer." (PMID 33081025, 2020). "This study investigated the amplification rates of the fibroblast growth factor receptor genes FGFR1, FGFR2, and FGFR3 in patients with breast cancer." (PMID 32852708, 2020). "Various aberrations in the fibroblast growth factor receptor genes FGFR1, FGFR2, and FGFR3 are found in different cancers, including breast cancer (BC)." (PMID 32852708, 2020). "For example, miR-99a can inhibit proliferation, migration, and invasion by directly regulating fibroblast growth factor receptor 3 (FGFR3) in breast cancer." (PMID 33066509, 2020). "The aim of this study was to investigate the amplification rates of FGFR1, FGFR2, and FGFR3 in patients with breast cancer and their impact on prognosis." (PMID 32852708, 2020). "Accordingly to Next Generation Sequencing (NGS) investigating FGFR levels in breast cancer, low levels of FGFR3 and FGFR4 were detected." (PMID 32188012, 2020). "Taken together, our findings support an important role for miR-99a in breast cancer, both as a regulator of oncogene FGFR3 and as a tumor suppressor that results in a significant decrease in breast cancer cell proliferation, invasion, and migration." (PMID 32038996, 2019). "The dual luciferase assay revealed that miR-99a directly targets FGFR3 by binding its 3′ UTR in breast cancer." (PMID 32038996, 2019). "In this paper, the relationship between the expression of miR-99a and that of FGFR3 was negatively correlated in breast cancer, and FGFR3 was directly regulated by miR-99a." (PMID 32038996, 2019). "The promising anti-cancer effects of PD173074 have also been translated into a xenograft tumor model of breast cancer in BALB/c mice where 4T1 xenograft tumor growth was remarkably suppressed by this FGFR1/FGFR3 dual inhibitor." (PMID 28900173, 2017). "We carried out a case-control study to investigate associations of variants in FGFR3 and FGFR4 with breast cancer in women from Heilongjiang Province." (PMID 26431494, 2015).
breast carcinoma (continued). "Whilst upregulation of this oncogene occurs most frequently in low-grade non-invasive tumors, recent data reveal increased FGFR3 expression characterizes a common sub-type of invasive UCC sharing molecular similarities with breast cancer." (PMID 25071007, 2014). "To further study this finding, we silenced FGFR2 and FGFR3 using shRNA lentiviral particles in the mouse breast cancer cell line 4T1." (PMID 23185502, 2012). "Collectively, these findings suggest that FGFR3 may contribute to PARPi resistance and present a compelling target for overcoming PARPi resistance in breast cancer treatment." (PMID 40460005, 2025). "The miR-99a/FGFR3 axis plays a crucial role as a tumor regulator in breast cancer." (PMID 38807590, 2024). "Moreover, amplification of the FGFR3 gene has been characterized in less than 1% of breast cancer patients." (PMID 37296801, 2023). "Amplification of the FGFR3 gene has been found in less than 1% of breast cancer patients." (PMID 35193394, 2022). "Similarly, FGFR1 alternative FGFR1α/FGFR1β splicing was found to play a key role in breast cancer and FGFR3 splicing promoted aggressiveness in prostate cancer." (PMID 34830836, 2021). "TBK1 and FGFR3 have been used as treatment targets for HER2+ breast cancer." (PMID 33849068, 2021). "However, it has been reported that miR-99a reduced breast cancer cell proliferation, invasion and migration by targeting FGFR3." (PMID 34123357, 2021). "Other studies support the presence, albeit at low frequency, of FGFR3 alterations in breast cancer." (PMID 31987043, 2020). "It has been therefore suggested that FGFR3 may be considered as a promising target in the treatment of breast cancer patients exhibiting resistance to endocrine therapy." (PMID 33081025, 2020). "FGFR3 silencing inhibited proliferation, migration and invasion of breast cancer cells." (PMID 32038996, 2019). "Interestingly, overexpression of FGFR3 and IGF1R in breast cancer (more specifically in MCF-7 for FGFR3) has been observed in previous studies, each related to breast cancer expansion through stem cells." (PMID 30566622, 2019). "In conclusion, these results suggest that the miR-99a/FGFR3 axis is an important tumor regulator in breast cancer and might have potential as a therapeutic target." (PMID 32038996, 2019). "Even though, role of FGFR3 in breast cancer progression has not been studied well, splice variants of FGFR3 are known to localize to nucleus of breast epithelial cancer cells." (PMID 29455658, 2018). "Notably, four C-oncogenes (NOTH1, FGFR2 and MYC for the breast cancer and FGFR3 for the colorectal cancer) were found to be amplified but down-regulated in their corresponding cancer types." (PMID 23472150, 2013). "Therefore, p-Y158 PARP1 could be a better biomarker in predicting FGFR3-mediated PARPi resistance than p-FGFR in breast cancer tissues." (PMID 40460005, 2025). "Notably, 7 of these samples were hormone receptor+/HER2–, while one was hormone receptor– and HER2+, suggesting an association between FGFR3 mutations and hormone receptor–positive breast cancer subtypes rather than TNBC." (PMID 40460005, 2025).
breast carcinoma (continued). "Five of the 14 diabetes-related genes, FOXA1, KIF22, PAK4, MTA3, and FGFR3, were specifically highly expressed in only the ER+/PR+ and ER+/PR− subtypes but not ER−/PR+ and ER−/PR− through an analysis using 4032 patient tissue samples from Breast Cancer Gene Expression Miner v4.5." (PMID 39000600, 2024). "Furthermore, we showed that miR-1291 is associated with negative regulation of various RTKs pathways, such as the PI3K/AKT, IGFR1, and FGFR3 signaling pathways that have a pivotal role in the regulation of cancer proliferation, angiogenesis, and metastasis in breast cancer." (PMID 33343622, 2020). "Additionally, recent reports suggest that FGFR3 may participate in a molecular pathway leading to breast cancer development." (PMID 32179814, 2020). "Consequently, while the presence of FGFR3 deletions raises the possibility of context-dependent tumor suppressor roles in a subset of breast cancers, strong evidence also exists for a positive role for this receptor in breast cancer progression." (PMID 31987043, 2020). "Despite the presence of FGFR3 deletions in a subset of breast cancer patients, amplification and/or overexpression of FGFR3 is associated with poor prognosis in the Metabric dataset, and an immunohistochemical study in breast cancer also identified FGFR3 as a negative prognostic factor." (PMID 31987043, 2020). "Furthermore, the activation of FGFR3 reduced the sensitivity of breast cancer cells to tamoxifen and fulvestrant and might serve as a candidate therapeutic target gene." (PMID 32038996, 2019). "Among the diabetes-related genes, FOXA1, MTA3, PAK4, FGFR3, and KIF22 were highly expressed in HR+ breast cancer from 4032 breast cancer patient tissue samples using the Breast Cancer Gene Expression Omnibus." (PMID 39000600, 2024). "Among the six fusions identified in breast carcinoma samples of the 38 samples examined, three involved NOTCH2, and one each involved FGFR3, NTRK3, and BRAF." (PMID 38800398, 2024). "As FOXA1 had the most significant gene expression, we checked the correlation between FOXA1 and other diabetes-related genes such as PAK4, FGFR3, MTA3, and KIF22 using a database containing 3262 ER+/PR+ breast cancer patient tissue samples." (PMID 39000600, 2024). "This review explores the structure, signaling pathways, and implications of FGFRs, particularly FGFR1, FGFR2, FGFR3, and FGFR4, in ER+ breast cancer." (PMID 39040443, 2024). "For instance, FGFR3 expression is increased in tamoxifen-resistant breast tumours and FGFR3 activation in MCF7 cells activates the MAPK, PI3K and PLCγ pathways, confirming its putative role in breast cancer development and resistance to endocrine therapy." (PMID 35193394, 2022). "SNP rs2234909 and rs3135848 in FGFR3 and rs1966265 and rs351855 in FGFR4 were successfully genotyped in 747 breast cancer patients and 716 healthy controls using the SNaPshot method." (PMID 26431494, 2015). "Whilst recent data report upregulation of both FGFR3 and FOXA1 characterize the papillary (luminal breast cancer-like) molecular subtype of invasive UCC, these reports did not include low-grade tumors." (PMID 25071007, 2014). "In conclusion, our results demonstrate that FGFR1 is crucial for S115 breast cancer cell proliferation and tumor growth and angiogenesis, whereas FGFR2 and FGFR3 are less critical for the growth of these cells." (PMID 23185502, 2012). "In the breast cancer samples of the MSK-CHORD cohort, we found only 8 FGFR3-mutant samples, none of which harbored BRCA1/2 mutations." (PMID 40460005, 2025). "In contrast, FGFR2 and FGFR3 were not significantly correlated with any subgroup of breast cancer cell lines, whereas FGFR4 expression was elevated in HER2 and luminal cell lines." (PMID 33772015, 2021).
breast carcinoma (continued). "In the Metabric dataset, breast cancer patients with amplified and/or overexpressed FGFR3 (46 out of 1903, 2%) have a significant (p-value of 0.0204) worse overall survival compared to breast cancer patients without FGFR3 alterations." (PMID 31987043, 2020). "The FGFR-specific inhibitors NPV-BGJ398, AZD4547 and JNJ-42756493 are under development for treating lung and breast cancers with FGFR1 amplification, gastric cancer with FGFR2 amplification, cholangiocarcinomas with an FGFR2 fusion, and urothelial cancers with FGFR3 alterations." (PMID 31601997, 2019). "No relation was found between FGFR3 protein expression and clinicopathological features in breast cancer." (PMID 28056982, 2017). "FGFR3 and FGFR4 amplification are less common than FGFR1 and FGFR2 in breast cancer." (PMID 27489863, 2016). "A primary goal of the experiments reported here was to elucidate complete functional oncogene signatures for a small panel of SUM breast cancer cell lines, each of which is known to harbor a driving RTK oncogene activated by amplification (SUM-52/FGFR2, SUM-185/FGFR3, SUM-225/HER2, SUM-190/HER2)." (PMID 27153554, 2016). "In conclusion, we evaluated the associations of four SNPs in the FGFR3 and FGFR4 genes with breast cancer in Chinese women from northeastern China and confirmed the associations of SNPs rs1966265 and rs351855 with breast cancer." (PMID 26431494, 2015). "Pools of S115 mouse breast cancer cells expressing shRNA against FGFR1, 2 and 3 were created by lentiviral gene transfer, resulting in cells with downregulated expression of FGFR1, FGFR2 or FGFR3 (shR1, shR2 and shR3 cells, respectively) and shLacZ controls." (PMID 23185502, 2012). "A more subtle shift in FGFR3 expression from the cytoplasm to the nucleus, which has been observed in breast cancer, is not present in prostate cancer." (PMID 15655558, 2005). "SNPs in FGFR4 but not in FGFR3 were strongly correlated with breast cancer." (PMID 34830836, 2021). "We also treated mouse 4T1 breast cancer cells with shRNA lentiviral particles targeting FGFR1-3.The silencing efficiency was not as high as in S115 cells, but nevertheless FGFR2 and FGFR3 silencing also resulted in increased FGFR1 gene expression in these cells." (PMID 23185502, 2012).
thanatophoric dysplasia (67 papers, 2005 to 2026). "The current case report presents the postmortem examination findings of a 17-week-old female fetus displaying thanatophoric dysplasia type 1 (TD-1) due to a known fibroblast growth factor receptor 3 (FGFR3) gene mutation." (PMID 39778871, 2025). "Thanatophoric dysplasia (TD) is a severe and typically fatal skeletal disorder caused by mutations in the FGFR3 gene, often leading to perinatal death." (PMID 39493014, 2024). "Variant classification in the absence of clinical data only occasionally allows a definitive clinical diagnosis to be made (e.g., an FGFR3 variant in thanatophoric dysplasia)." (PMID 37285546, 2023). "Thanatophoric dysplasia is a rare, fatal, and sporadic form of skeletal dysplasia caused by a mutation in fibroblast growth factor receptor 3 (FGFR3)." (PMID 37915702, 2023). "Thanatophoric dysplasia (TD) is a rare, congenital, sporadic, and lethal skeletal dysplasia caused by de novo autosomal dominant mutation in the fibroblast growth factor receptor 3 (FGFR3) gene, located on chromosome 4p16.3." (PMID 37915702, 2023). "The mutation in FGFR3 (c.1949 A > T) is known to cause thanatophoric dysplasia, a severe short-limb dwarfism syndrome that is usually lethal in the perinatal period (OMIM #187601), which supports the findings of targeted-seq." (PMID 34789231, 2021). "Shorter cilia were also found in the cartilage of humans with thanatophoric dysplasia, and in cells overexpressing a pathological FGFR3 variant." (PMID 34207779, 2021). "Several FGFR3 de novo mutations were identified in thanatophoric dysplasia (TD) patients, including R248C, S249C, K650M, K650E95–99." (PMID 33116259, 2020). "Thanatophoric dysplasia is an uncommon, lethal skeletal dysplasia which is associated with mutation in the extracellular region of fibroblast growth factor receptor 3 (FGFR3)." (PMID 33520059, 2020). "Gain-of-function mutations of FGFR2 and FGFR3 cause Apert syndrome and thanatophoric dysplasia, which are characterized by unique and complex malformation of the cortex, including megalencephaly and polymicrogyria." (PMID 28489004, 2017). "In this study, human chondrosarcoma cells expressing constitutively active mutants of FGFR3 that cause thanatophoric dysplasia, SADDAN and achondrogenesis were treated in vitro with meclozine and this ameliorated abnormally suppressed cell proliferation." (PMID 26635999, 2015). "Acanthosis nigricans is associated with severe skeletal dysplasia caused by activating germline mutations of FGFR3 gene, including thanatophoric dysplasia and SADDAN syndrome." (PMID 25505998, 2014). "STAT activation is implicated in mediating the effects of FGFR3 mutations associated with thanatophoric dysplasia." (PMID 22174695, 2011). "As gonadal mosaicism for the R248C FGFR3 mutation cannot be entirely excluded, a risk of having offspring with thanatophoric dysplasia exists." (PMID 21639936, 2011). "S249C FGFR3 mutation has been initially described in constitutional DNA from individuals with thanatophoric dysplasia." (PMID 15869706, 2005). "Additionally, we detected FGFR3 variants in five patients with Thanatophoric dysplasia (types 1 (OMIM: #187600) and type 2 (OMIM: #187601) and three with Muenke syndrome (OMIM: #602849)." (PMID 40130161, 2025). "Several FGFR3 de novo mutations were identified in thanatophoric dysplasia (TD) patients." (PMID 36358993, 2022). "Less commonly interpedicular narrowing may be found in other entities with FGFR3 mutations, such as hypochondroplasia and the lethal thanatophoric dysplasia." (PMID 32580780, 2020). "Meclozine also ameliorated abnormally suppressed proliferation of human chondrosarcoma (HCS-2/8) cells that were infected with lentivirus expressing constitutively active mutants of FGFR3-K650E causing thanatophoric dysplasia, FGFR3-K650M causing SADDAN, and FGFR3-G380R causing ACH." (PMID 24324705, 2013).